PRMT1 (protein arginine methyltransferase 1)
Diseases named in the same sentence as PRMT1 in open-access papers (continued):
Sharing a sentence is not in itself a finding about the gene and the disease.
lung cancer (31 papers, 2012 to 2025). A malignant neoplasm involving the lung. "Here, we discovered that a specific isoform of type I protein arginine methyltransferases (PRMT), namely, PRMT1, enables lung cancer cells with EGFR or KRASG12C driver mutations and high STAT1 activity to persist through targeted drug treatments." (PMID 39699269, 2025). "In this study, we investigated the underlying mechanism of PRMT6 and its cooperation with PRMT1 to form a heteromer as a driver of lung cancer." (PMID 38303720, 2024). "The upregulation of PRMT1 in lung cancer has also been associated with chemotherapeutic drug resistance." (PMID 38326807, 2024). "Upregulation of PRMT1 expression in lung cancer is linked to a decrease in E-cadherin and an increase in N-cadherin levels, which stimulates cell migration, invasion, and metastasis." (PMID 34006904, 2021). "For example, overexpression of PRMT1 is linked to lung cancer, while aberrant expression levels of PRMT1, -4, and -5 are observed in breast tumors." (PMID 29208765, 2018). "By studying PRMT1 knockdown alone and in combination with oncogene-targeting drugs, we found that suppression of oncogenic signaling in lung cancer confers a collateral dependency on PRMT1 in persistent cancer cells." (PMID 39699269, 2025). "In lung cancer, PRMT1 methylates TWIST1 at R34, regulating genes involved in cytoskeletal remodeling and cell motility to promote metastasis." (PMID 41204384, 2025). "Our study identified PRMT1 as the key type I PRMT isoform mediating persistence in STAT1-high lung cancer." (PMID 39699269, 2025). "We established targeted therapy-sensitive xenograft models using two lung cancer cell lines expressing PRMT1-targeting shRNA: one EGFRmut model (HCC827) and one KRASG12C model (H1373)." (PMID 39699269, 2025). "PRMT1 is abnormally expressed in a variety of cancers, including lung cancer, gastric cancer, prostate cancer, colon cancer, pancreatic cancer, and liver cancer." (PMID 39741976, 2024). "Flap endonuclease 1 (FEN1), playing a key role in DNA replication and repair, is maintained at high expression levels by PRMT1, crucial for DNA repair and chemotherapy resistance in lung cancer cells." (PMID 38525426, 2024). "To demonstrate the proof of principle for the targeting of the PRMT1/PRMT6 heteromer in lung cancer, we showed that disrupting the complex reduced cell viability in LC PDOs from a Caucasian male (PDXO) and a Black/AA female (PDO)." (PMID 38303720, 2024). "In summary, our study identified a unique role of the PRMT1/PRMT6 heteromer in driving lung cancer development which likely contributes to cancer health disparities in Black/AA men." (PMID 38303720, 2024). "Previous studies have found that PRMT1 expression is aberrantly expressed in various cancers, including gastric cancer, lung cancer, and colorectal cancer." (PMID 39741976, 2024). "Together, our results implicate that high PRMT6 expression cooperates with PRMT1 to drive higher incidence and mortality rates of lung cancer in Black/AA men." (PMID 38303720, 2024). "In non–small cell lung cancer, PRMT1 has been suggested to be a regulator of epithelial-to-mesenchymal transition." (PMID 36669591, 2023). "The upregulation of PRMT-1 has been found to promote the proliferation and transformation of cancer cells in various cancers, including lung cancer, breast cancer and colon cancer." (PMID 37444572, 2023). "The upregulation of PRMT1 is involved in a diverse range of cancer, such as lung cancer, and there is an urgent need to develop novel and potent PRMT1 inhibitors." (PMID 35755248, 2022). "Numerous studies have addressed the regulatory mechanisms and roles of PRMT1 in human cancers including breast, prostate, lung cancer, and leukemia, but little is known about the regulatory roles of PRMT1 in CRC progression." (PMID 33853662, 2021). "PRMT1-mediated Twist1 methylation is involved in the regulation of the epithelial-mesenchymal transition (EMT) in lung cancer cells." (PMID 34006904, 2021).
lung cancer (continued). "Recent studies have demonstrated PRMT1/5 to fine-tune the degradation of anti-apoptotic protein CFLARL in human lung cancer cells." (PMID 34200178, 2021). "Herein, we utilize this INEI to carry N, N′-(Sulfonyldi-4,1-phenylene)bis(2-chloroacetamide) (TE-C-5003), which is a selective protein arginine methyltransferase 1 (PRMT1) inhibitor, to treat the lung cancer mice model." (PMID 32212935, 2020). "We also overexpressed PRMT1 in lung cancer cells for 24 h and then treated the cells with 2 μmol/L doxorubicin for 24 h." (PMID 30736843, 2019). "First, over‐expression of BTG2 is known to inhibit proliferation of cells and invasion in some tumours, including lung cancer cells, and acts as an anti‐proliferation gene in cooperation with PRMT1." (PMID 29656435, 2018). "Accordingly, in this study we investigated the impact of UCP2 and PRMT1 on the fate of human lung cancer cells (A549, Calu-3 and H1299) as well as on patients suffering from lung carcinoma." (PMID 29113301, 2017). "The finding that viability and proliferation of lung carcinoma cells was strongly increased in case of upregulated PRMT1 and UCP2 expression further supports a link between the expression of these two proteins and cancer cells’ perilousness." (PMID 29113301, 2017). "Finally, we found that targeting PRMT1 to reduce persistence is more effective in lung cancer models with intact versus deleted chromosome 5q31.1, a region enriched with JAK-STAT pathway genes, suggesting a potential stratification criterion." (PMID 39699269, 2025). "Data from orthogonal approaches (siRNA and shRNA knockdown) and various models (EGFRmut and KRASG12C lung cancer; in vitro and in vivo) consistently show that knockdown of PRMT1 reduces persistence when combined with oncogene-targeting drugs but does not reduce general cell fitness when used alone." (PMID 39699269, 2025). "Research suggests that the PRMT1 inhibitor C‐7280948 may enhance the radiosensitivity of lung cancer by modulating the PRMT1/PKP2/β‐catenin/LIG4 signaling pathway, thereby overcoming radiation resistance and improving patient outcomes." (PMID 41256732, 2025). "Thus, it is of interest to determine the role of ILF2 in lung cancer development and in mediating the function of the PRMT1/PRMT6 heteromer in vivo." (PMID 38303720, 2024). "Targeting PRMT1 holds promise as a potential therapeutic strategy in lung cancer." (PMID 38326807, 2024). "Thus, the next step is to utilize genetically engineered mouse models to demonstrate the role of PRMT1/PRMT6 heteromer in lung cancer." (PMID 38303720, 2024). "Specific targets, such as PRMT1, KDM6B, CARM1, BRD4, and EZH2, have been shown to be associated with malignant phenotypes of lung cancer, influencing cell proliferation and metastatic processes (regulation of epithelial–mesenchymal transition and cell invasion)." (PMID 36233212, 2022). "PRMT1 is thus considered as a potential therapeutic target for lung cancer and metastasis." (PMID 35755248, 2022). "Furthermore, upregulation of PRMT1 correlates with high expression of FEN1 in lung cancer due to stabilization of the FEN1 protein via PRMT1-mediated arginine methylation." (PMID 34006904, 2021). "Hence, UCP2' impact on the MCUC in case of elevated PRMT1 activity is further demonstrated by the poor survival prognosis of lung carcinoma patients with combined upregulation of UCP2 and PRMT1." (PMID 33614647, 2021). "However, the role of PRMT1 in lung cancer progression and metastasis remains incompletely understood." (PMID 25847239, 2015). "Thus, PRMT1 not only represents a unique class of EMT regulators but also represents a potential new class of drug targets for future therapeutic treatments of lung cancer." (PMID 25847239, 2015). "However, the upstream regulator/s of PRMT1 catalytic activities in lung cancer remain to be identified." (PMID 25847239, 2015).
lung cancer (continued). "However, the in vivo role of ILF2 in driving lung cancer and whether the function of PRMT1/PRMT6 heteromer is mediated via ILF2 still await further investigation." (PMID 38303720, 2024). "Future investigations are warranted to explore the use of combining current cancer-debulking therapies with novel persistence-eliminating PRMT1 inhibitors in more extensive disease settings beyond EGFRmut and KRASG12C lung cancer." (PMID 39699269, 2025). "In non‐small cell lung cancer (NSCLC), PRMT1 promotes the Warburg effect, and its stability is regulated by USP7." (PMID 41256732, 2025). "In this study, we reveal a novel, methyltransferase‐independent role of PRMT1 in upregulating IGF2BP2 expression in HNSCC, as well as in HCC and lung cancer cells." (PMID 40270464, 2025). "We showed both in vitro and in vivo that PRMT1 knockdown enhanced the efficacy and durability of oncogene-targeting drugs in EGFRmut and KRASG12C lung cancer models." (PMID 39699269, 2025). "Additional mechanisms include PRMT1‐mediated methylation of PKP2 and SOX2, which contributes to radioresistance and chemoresistance in lung cancer." (PMID 41256732, 2025). "Regarding FEN1 regulation, PRMT1-mediated methylation stabilizes FEN1 protein levels, improving DNA repair capacity and therapy resistance in lung cancer cells." (PMID 41204384, 2025). "Taken together, our results suggest that the increased expression of ILF2 by the PRMT1/PRMT6 heteromer promotes cell proliferation and likely contributes to lung cancer health disparities in Black/AA men." (PMID 38303720, 2024). "We demonstrated that PRMT1/PRMT6 heteromer played a critical role in cell proliferation and perhaps lung cancer development." (PMID 38303720, 2024). "In lung cancer cells, downregulation of PRMT5 or overexpression of PRMT1 promotes apoptosis induced by docetaxel and pemetrexed by modulating the degradation of the anti-apoptotic protein CFLARL." (PMID 38525426, 2024). "To investigate the efficacy of PRMT5 inhibition, we treated oral and lung cancer cells with single and combined PRMT5 and PRMT1 inhibitors (PRMT5/1i)." (PMID 38709899, 2024). "We demonstrated that PRMT1 and PRMT6 formed a heteromer, and breaking this heteromer with a peptide inhibitor reduced cell proliferation and viability in NSCLC cell lines and lung cancer organoids." (PMID 38303720, 2024). "Studies have shown that treatment with C-7280948 can eliminate radiation resistance induced by PRMT1-mediated methylation of PKP2, making it a potential radiosensitizer in lung cancer." (PMID 38326807, 2024). "PRMT-1 is a regulator of EMT that increases the invasive and migratory properties, which promotes lung cancer progression and metastasis." (PMID 37444572, 2023). "We also demonstrated that PRMT1 and PRMT5 had opposing effects on chemotherapeutic agent-mediated apoptosis in lung cancer cells." (PMID 30736843, 2019). "Elevated levels of mitochondrial respiration in lung carcinoma cells with combined overexpression of UCP2 and PRMT1 are in line with this suggestion." (PMID 29113301, 2017). "Our results from cell viability experiments with human lung carcinoma cells as well as analysis of lung carcinoma patient's overall survival reveal a positive impact of UCP2 and PRMT1 on cancer cells." (PMID 29113301, 2017). "Particularly, PRMT1 and PRMT6, which catalyze asymmetric dimethylarginine formation, were shown to be significantly up-regulated in lung cancer compared with adjacent normal tissue." (PMID 25847239, 2015). "siRNA-mediated knockdown of PRMT1 and PRMT6 was found to lead to suppression of lung cancer cell growth, most probably by influencing G1-S transition in the cell cycle." (PMID 23202904, 2012). "Analysis of PRMT1 and PRMT5 transcript expression using the R2 platform focusing on the Filion dataset of sarcomas that includes Ewing sarcoma patients alongside other fusion-positive sarcomas and breast and lung cancer datasets." (PMID 40823091, 2025).
lung cancer (continued). "We found that PRMT1 and PRMT5 expression, along with MEP50 the obligate cofactor of PRMT5, are generally higher in multiple sarcoma types, including EWSR1::FLI1 and EWSR1::ERG fusion-positive ES tumours, than in breast and lung cancer." (PMID 40823091, 2025). "PRMT1-mediated methylation of twist-related protein 1 (TWIST1) induces EMT, characterized by reduced E-cadherin expression and increased N-cadherin expression, thereby promoting migration and invasion of lung cancer cells." (PMID 38525426, 2024). "As a result, we investigated whether silencing PRMT5 and PRMT1 affected FXR1, FXR2 and FMRP levels in oral and lung cancer cells." (PMID 38709899, 2024). "Since viability as well as proliferation of lung cancer cells were strongly affected by expression levels of UCP2 and PRMT1, we analyzed the survival of lung carcinoma patients with different mRNA expression patterns of UCP2 and PRMT1." (PMID 29113301, 2017). "Similarly to previously published studies on breast, colon and bladder cancers, elevated PRMT1 and PRMT6 expression has recently been found in various types of lung cancer including SCLC and NSCLC." (PMID 23202904, 2012). "Interestingly, knockdown of IRF1 alone did not significantly impact persistence with PRMT1 knockdown in three tested STAT-high lung cancer cell lines." (PMID 39699269, 2025). "Disrupting PRMT1/PRMT6 heteromer by a competitive peptide reduced proliferation in non-small cell lung cancer cell lines and patient-derived organoids, therefore, giving rise to a more strategic approach in the treatment of Black/AA men with lung cancer and to eliminate cancer health disparities." (PMID 38303720, 2024). "Moreover, PRMT1 overexpression, and UCP2 collectively normalize mitochondrial Ca2+ uptake, ensuring oxidative phosphorylation (OXPHOS), aligning with the observed elevated levels of mitochondrial respiration in lung carcinoma cells." (PMID 38326807, 2024). "The identification of PRMT5 and PRMT1 as CFLARL regulators involved in cellular apoptosis may help in developing new strategies to increase the sensitivity of cancer cells to chemotherapy, which may eventually benefit lung cancer treatments." (PMID 30736843, 2019). "Thus, PRMT1 appears to act as an important regulator of tumor metastasis in lung cancer, and the effects of PRMT1 knockdown on tumor metastasis were not due to apoptotic cell death." (PMID 25847239, 2015). "As PRMT1 is a major type I PRMT, it is not surprising that its enhanced expression is mirrored by increased ADMA content in systemic circulation in lung cancer patients as compared to nontumor control subjects." (PMID 23202904, 2012).
colorectal cancer (27 papers, 2021 to 2026). A primary or metastatic malignant neoplasm that affects the colon or rectum. "Two clinical reports demonstrated the unfavorable prognosis associated with PRMT1 expression in colorectal cancer (CRC) patients by discussing the respective involvement of PRMT1-v1 and PRMT-v2 isoforms." (PMID 34833023, 2021). "In addition, TRIM21 binds to PRMT1 via its SPRY domain to promote the ubiquitination and degradation of the oncogene PRMT1 in a K48-linked manner, thereby inhibiting the metastasis of colorectal cancer cells." (PMID 40735642, 2025). "Additionally, PRMT1, -4, and -5 have been implicated in the progression of colorectal cancer (CRC)." (PMID 39826691, 2025). "A previous study has demonstrated that the methylations on the EGFR extracellular domain mediated by PRMT1 enhance receptor function in colorectal cancer cells, affecting the EGF-EGFR binding affinity to promote tumorigenesis." (PMID 40612681, 2025). "In colorectal cancer, PRMT1 cooperates with chromatin subfamily A member 4 (SMARCA4) to activate EGFR signaling, promoting malignant transitions." (PMID 40612681, 2025). "For the first time, we uncovered that TRIM21, a tumor suppressor gene in colorectal cancer, binds to PRMT1 using its SPRY domain and acts as an E3 ubiquitin ligase, promoting the ubiquitination and degradation of the oncogene PRMT1 in a K48-linked manner." (PMID 39890802, 2025). "The inhibitor C7280948, also specific for PRMT1, has been shown to be effective against proliferation, migration, and invasion of colorectal cancer cells." (PMID 40001488, 2025). "PRMT1 was highly expressed in the colorectal cancer tissues and exhibited oncogenic function in colorectal cancer, which was associated with poor overall survival in advanced colorectal cancer patients." (PMID 37737256, 2023). "To further evaluate the potential clinical value of PRMT1 in the treatment of MM, we selected the PRMT1-selective small-molecule inhibitor C7280948, which has been reported to suppress cell proliferation, migration, and invasion in colorectal cancer." (PMID 37558663, 2023). "PRMT1 is involved in the process of carcinogenesis in amounts of tumors, such as acute myeloid leukemia, pancreatic cancer, and colorectal cancer." (PMID 37737256, 2023). "PRMT1 has been previously observed to modulate EGFR signaling by two mechanisms: (i) by methylating histone H4 (H4R3me2a) on its promoter in colorectal cancer (CRC) and glioblastoma cells and (ii) by methylating EGFR in CRC and TNBC cells." (PMID 35053470, 2022). "PRMT1 which triggers asymmetric dimethylation of histone H4 on arginine 3 (H4R3me2a) is upregulated in human colorectal cancer (CRC) and is essential for cell proliferation." (PMID 33853662, 2021). "Nonetheless, we provide evidence to show that SMARCA4 promotes colorectal cancer cell proliferation by interacting with PRMT1 to activate TNS4 and EGFR transcription." (PMID 33853662, 2021). "As we have previously shown in colorectal cancer, PRMT1 and PRMT5 expression can be upregulated both in colonic tumors and adjacent tissue." (PMID 34439753, 2021). "Additionally, SMARCA4 recruited by PRMT1-mediated H4R3me2a enhances EGFR signaling and TNS4 expression in colorectal cancer, with elevated PRMT1 or SMARCA4 levels positively correlating with increased EGFR and TNS4 expression and decreased overall survival." (PMID 40906372, 2025). "To explore whether PRMT1 is involved in the abnormal glycolysis process of colorectal cancer, we overexpressed or knocked down PRMT1 in HCT116 and DLD1 cells to investigate its potential effects on glucose metabolism." (PMID 38402202, 2024). "Here, we report that PRMT1 enhances colorectal cancer cell glycolysis and tumorigenesis." (PMID 38402202, 2024). "Taken together, our data strongly suggest that PRMT1 enhances colorectal cancer cell glycolysis." (PMID 38402202, 2024).